CCL5 (C-C motif chemokine ligand 5)
Description:
Chemoattractant for blood monocytes, memory T-helper cells and eosinophils. Causes the release of histamine from basophils and activates eosinophils. May activate several chemokine receptors including CCR1, CCR3, CCR4 and CCR5. One of the major HIV-suppressive factors produced by CD8+ T-cells. Recombinant RANTES protein induces a dose-dependent inhibition of different strains of HIV-1, HIV-2, and simian immunodeficiency virus (SIV). The processed form RANTES(3-68) acts as a natural chemotaxis inhibitor and is a more potent inhibitor of HIV-1-infection. The second processed form RANTES(4-68) exhibits reduced chemotactic and HIV-suppressive activity compared with RANTES(1-68) and RANTES(3-68). May also be an agonist of the G protein-coupled receptor GPR75, stimulating inositol trisphosphate production and calcium mobilization through its activation. Together with GPR75, may play a role in neuron survival through activation of a downstream signaling pathway involving the PI3, Akt and MAP kinases. By activating GPR75 may also play a role in insulin secretion by islet cells.
Synonyms: TCP228; D17S136E; SCYA5; RANTES; SISd; MGC17164; SIS-delta; eoCP
Tractability: Small molecule: a structure with a bound ligand is known; a high-quality ligand is known; it belongs to a druggable protein family. Antibody: its Gene Ontology location is reachable by antibodies, with high confidence; UniProt places it where antibodies can reach, with medium confidence; UniProt predicts a signal peptide or a membrane-spanning region. PROTAC: ubiquitination databases record sites on it; its protein half-life has been measured; a small molecule that binds it is known.
Target class: Secreted protein
Gene: Protein-coding gene on chromosome 17 (35,871,491 to 35,880,793, reverse strand). Ensembl gene ENSG00000271503.
Subcellular location: Secreted
Pathways (Reactome):
Signal Transduction: Chemokine receptors bind chemokines; G alpha (i) signalling events
Immune System: Interleukin-10 signaling
Gene Ontology:
Molecular function: CCR1 chemokine receptor binding; CCR5 chemokine receptor binding; chemoattractant activity; chemokine activity; chemokine receptor antagonist activity; chemokine receptor binding; identical protein binding; phosphatidylinositol-4,5-bisphosphate phospholipase C activity; phospholipase activator activity; protein binding; protein homodimerization activity; protein kinase activity; receptor signaling protein tyrosine kinase activator activity; CCR chemokine receptor binding; CCR4 chemokine receptor binding
Biological process: calcium ion transport; cell-cell signaling; cellular response to fibroblast growth factor stimulus; cellular response to interleukin-1; cellular response to tumor necrosis factor; cellular response to type II interferon; cellular response to virus; chemokine (C-C motif) ligand 5 signaling pathway; chemokine-mediated signaling pathway; eosinophil chemotaxis; exocytosis; G protein-coupled receptor signaling pathway; host-mediated suppression of viral transcription; intracellular calcium ion homeostasis; leukocyte cell-cell adhesion; negative regulation of G protein-coupled receptor signaling pathway; negative regulation of T cell apoptotic process; negative regulation of viral genome replication; neutrophil activation; phospholipase D-activating G protein-coupled receptor signaling pathway; positive regulation of calcium ion transport; positive regulation of cell adhesion; positive regulation of cell migration; positive regulation of cell-cell adhesion mediated by integrin; positive regulation of G protein-coupled receptor signaling pathway; and 33 more
Cellular component: membrane; extracellular region; cytoplasm
Genetic constraint (gnomAD): Loss-of-function variants: 3 observed, 5.49 expected, observed/expected ratio (o/e) 0.55, 90% interval 0.25 to 1.39. That is too few expected variants to judge how well the gene tolerates losing a copy. Missense variants: 162 observed, 166.65 expected, observed/expected ratio (o/e) 0.97, 90% interval 0.86 to 1.11. Synonymous variants: 59 observed, 65.96 expected, observed/expected ratio (o/e) 0.89, 90% interval 0.73 to 1.11.
Homologues: Orthologues: chimpanzee CCL5 (100% identical), macaque CCL5 (96% identical), rabbit CCL5 (89% identical), guinea pig CCL5 (88% identical), pig CCL5 (84% identical), mouse Ccl5 (80% identical), dog CCL5 (77% identical), tropical clawed frog ccl5 (44% identical), zebrafish ccl35.1 (30% identical), zebrafish ccl35.2 (30% identical). Paralogues in human: CCL3L3 (49% identical), CCL3 (48% identical), CCL4 (46% identical), CCL4L2 (43% identical), CCL16 (41% identical), CCL15 (38% identical), CCL23 (38% identical), CCL14 (37% identical), CCL18 (37% identical), CCL26 (37% identical), CCL11 (34% identical), CCL8 (33% identical), and 14 more.
Diseases named in the same sentence as CCL5 in open-access papers:
CCL5 is named in the same sentence as 707 diseases in open-access papers, as found by Europe PMC text mining. Sharing a sentence is not in itself a finding about the gene and the disease. The quoted sentences say what the papers report.
breast cancer (349 papers, 2007 to 2026). A primary or metastatic malignant neoplasm involving the breast. "Human epidermal growth factor receptor 2 (Her2) (alias receptor tyrosine-protein kinase erbB-2 (ERBB2) or cluster of differentiation 340 (CD340))-positive breast cancer patients have high serum levels of CCL5 associated with poor prognosis." (PMID 40076892, 2025). "In patients with periodontitis, gingival disease facilitates lymph node metastasis, particularly in breast cancer, which is associated with increased expression of CCL5, CCL2, and CXCL5." (PMID 38139161, 2023). "Eskandari-Nasab and colleagues demonstrated that CCL5 rs2107538 variants were associated with an increased risk of breast cancer." (PMID 36983384, 2023). "Recently, it has been observed that the expression of CCL5 is strongly associated with breast cancer progression, especially in TNBC." (PMID 36765778, 2023). "YAP1 expression was positively correlated with Notch1 in breast cancer, and CCL5/CCR5 activated YAP in tumor-associated macrophages." (PMID 37759462, 2023). "Although most studies have shown that high CCL5 correlates with poor outcomes in breast cancer, correlative studies have also shown a positive association between CCL5 and tumor-infiltrating lymphocytes (TILs) in TNBC." (PMID 37759462, 2023). "The CCL5 variants have been associated with an increased risk of several cancers including: gastric cancer, prostate cancer, and breast cancer." (PMID 36983384, 2023). "CCL5, a product of cancer cells and macrophages, is usually linked to a worse outcome in diverse types of breast cancer." (PMID 38045829, 2023). "In Her2+ BCa, Traztuzamab resistance of Her2+ breast cancer was linked to hyperactivation of CCL5/CCR5 signaling, and shown to be attenuated by maraviroc." (PMID 37759462, 2023). "Their results indicated that individuals carrying the CCL5 rs2107538-GA or GA + AA genotypes or A allele had higher risk of developing breast cancer compared to those carrying the CC genotype or C allele." (PMID 36983384, 2023). "Lactate also activates breast cancer-associated macrophages and upregulates CCL5 and CCR5 expression by activating the NOTCH, TGFβ, and AMPK pathways, promoting EMT, migration, and aerobic glycolysis in BC cells through a positive feedback loop." (PMID 36618350, 2022). "In multivariable logistic regression analysis, a higher polygenic risk scores for plasma CCL5 was inversely associated with breast cancer (OR for the highest tertile = 0.94, 95% CI = 0.89–1.00, p = 0.045)." (PMID 36685922, 2022). "In this Mendelian randomization study of 30 plasma chemokines, we found an inverse association between genetically predicted plasma CCL5 and breast cancer in both the two-sample and one-sample analyses." (PMID 36685922, 2022). "Our analysis found an inverse association between CCL5 and breast cancer, with a similar effect size in a recent phenome-wide Mendelian randomization." (PMID 36685922, 2022). "The expression of CCL2 and CCL5 is associated with inflammation and with advanced breast cancer and tumor progression." (PMID 34228231, 2021). "Strikingly, we found that cancer-associated fibroblasts secreted greater than 60-fold more CCL5 protein than any of the breast cancer cells." (PMID 33868996, 2021). "The high level of co-expression of TNFRSF4 and CCL5 in the METABRIC data set suggests that either gene is associated with immune infiltration in breast cancer tumors." (PMID 34226941, 2021). "CCL5 and its receptor have been reported to be associated with the progression and drug resistance of many tumors, including breast cancer." (PMID 34771505, 2021). "IL-6, IL-8, CCL2, and CCL5 have been found to be stimulators of the proliferation, survival, and invasion of breast cancer cells and are linked to an advanced stage of breast cancer." (PMID 34912237, 2021). "CCL5 is expressed by malignant epithelial cells in breast carcinoma and is associated with advanced disease progression." (PMID 33968034, 2021).
breast cancer (continued). "CCL5 secreted by tumor cells and other cells in the breast cancer tumor microenvironment can recruit tumor-associated macrophages into the tumor microenvironment." (PMID 32963529, 2020). "CCL5, in association with the negativity for estrogen receptor (ER), was suggested as a biomarker for disease progression in stage II breast cancer patients." (PMID 32630699, 2020). "We investigated the potential association of 9 SNPs associated with the CCL5 signaling pathway and the clinical and pathological characteristics of breast cancer in our cohort." (PMID 31921621, 2019). "We also showed the functional implication of CCL5 breast cancer susceptibility locus and correlated the risk alleles of CCL5 SNPs with low levels of serum CCL5." (PMID 31921621, 2019). "The breast cancer risk alleles CCL5 rs2280789-G and CCL5 rs2107538-T were highly associated in a dose-dependent manner with low levels of CCL5 in sera of patients with breast cancer (all patients without subtype stratification)." (PMID 31921621, 2019). "The OR of breast cancer associated with the CCL5 rs2107538-T/T genotype was 2.74 (P = 0.004) and that of HS6ST3 rs1924587-C/C genotype was 1.52 (P = 0.021)." (PMID 31921621, 2019). "ER− breast cancer is associated with elevated NF-κB activity, and shows increased expression of certain cytokines (IL-6, IL-8) and chemokines (CCL5, MCP-1 [CCL2])." (PMID 30736340, 2019). "CCL5 has been implicated in luminal type breast cancer by modulating the phenotype of CD4+ T cells and in ER-positive breast cancers by promoting macrophage influx." (PMID 31921621, 2019). "In a dose-dependent manner, the breast cancer risk alleles CCL5 rs2280789-G and CCL5 rs2107538-T were predictors of low levels of CCL5 expression in whole blood and lymphocytes of GTEx dataset (P = 7 × 10−6 and 6 × 10−8, respectively)." (PMID 31921621, 2019). "Regarding breast cancer, it has been described that CCL5-deficient mice are resistant to mammary tumor growth." (PMID 29559701, 2018). "Notch has been reported to positively regulate CCL5 expression in multiple myeloma-associated BMSCs and in breast cancer." (PMID 30154786, 2018). "In stage II breast cancer, high expression of CCL5 (assessed by immunohistochemistry) has been associated with disease progression." (PMID 29559701, 2018). "It is also reported that lower expression of RKIP in breast cancer is associated with higher levels of CCL5, as well as a higher probability of metastasis and poor prognosis." (PMID 30483271, 2018). "Strikingly, pluripotency correlated with CCL5 expression, which is a prominent factor in stromal gene expression signatures and linked to worse prognosis in breast cancer." (PMID 28372546, 2017). "Chemokines, including CXCL3, CXCL12, CXCL13, CCL21, CCL2 and CCL5, have been implicated in promoting the malignant phenotype in breast cancer." (PMID 29216863, 2017). "Viewed altogether, the data indicate that CCL5 activation of CCR5 in breast cancer cells is associated with increased metabolic activity during tumor onset." (PMID 29216863, 2017). "EO771 and 4T1 breast cancer cells were stably transduced with lentiviral vector (LVs) encoding CCL5 short hairpin RNA (generated with either seed sequence 2 or 3) and orthotopically implanted into mice." (PMID 27863423, 2016). "CCL5 produced by mesenchymal stem cells (MSCs) acts to induce malignancy-associated changes in breast cancer cells to promote spread through binding with its cognate receptor, CCR5." (PMID 27863423, 2016). "The survival data are in contrast to association of CCL5 protein expression with metastatic potential in basal breast cancer." (PMID 26173622, 2015). "Our loss- and gain-of-function CCL5 expression rescue experiments indeed demonstrated the causal role of CCL5 in RKIP-mediated regulation of breast cancer cells invasion in vitro." (PMID 26375811, 2015).
breast cancer (continued). "Elevated levels of CCL5 in plasma and at the primary tumor site of breast cancer patients have been previously associated with progressive and more advanced disease and with axillary lymph node metastasis." (PMID 26560478, 2015). "Nonetheless, increased CCL5 expression was associated with better survival in HER2+ breast cancer (p-value of 0.01)." (PMID 26173622, 2015). "Here, we show that RKIP has a causal role in the regulation of CCL5 expression in breast cancer cells." (PMID 26375811, 2015). "Although CCL5 is also linked to macrophage infiltration in animal models of breast cancer, in human breast xenografts, CCL5 expression correlates negatively with macrophage recruitment, implying the participation of other chemokines." (PMID 25165728, 2014). "CCL5 expression by breast tumor cells represents a valuable prognostic factor for detection of stage II breast cancer patients who are at risk for disease progression." (PMID 24523569, 2014). "Tumor expression of CCL5 promotes breast cancer progression, and both SNPs have been associated with decreased risk of prostate cancer in men of African descent." (PMID 23991131, 2013). "Among AAs, carriers of the variant allele for CCL5-rs2280789 were 48% more likely to be diagnosed with ER positive breast cancer (P=0.03)." (PMID 23991131, 2013). "The results of our study indicate that significant associations exist between CCL2 & CCL5 and TNFα & IL-1β in breast cancer, along different stages of disease course." (PMID 21486440, 2011). "We provide evidence to a coordinated expression of the inflammatory chemokines CCL2 & CCL5 and the inflammatory cytokines TNFα & IL-1β in breast cancer, all having causative roles as tumor-promoting factors in this disease." (PMID 21486440, 2011). "Similarly, we also observed immune genes ADRB1 and chemokine ligand CCL5, which were associated with breast cancer prognosis." (PMID 38676834, 2024). "Since higher expression of CCL5 is associated with poorer overall survival in patients with breast cancer, this chemokine may be an attractive target of DHEA in adjuvant therapy for improving clinical care and decreasing mortality from TNBC patients." (PMID 36765778, 2023). "Furthermore, high serum CCL5 level involved in cancer immune reactions is remarkably associated with longer disease-free survival and OS of patients with early breast cancer." (PMID 36090993, 2022). "In conclusion, we found that lower plasma CCL5 was causally associated with breast cancer, while plasma and tumor-derived CCL19 might be associated with increased survival of breast cancer patients." (PMID 36685922, 2022). "Interestingly, e-cigarettes also promote breast cancer cell growth and metastatic lung colonization, mediated by cross-talk with tumor-associated macrophages via CCL5 and VCAM-1 pathways in an animal study." (PMID 35406378, 2022). "A higher plasma CCL5 was inversely associated with breast cancer (OR = 0.89, 95% CI: 0.85 to 0.94, p < 0.001), which was primarily attributed to the luminal A and luminal B subtypes (OR for luminal A = 0.88, 95% CI: 0.82 to 0.94; OR for luminal B = 0.80, 95% CI: 0.69–0.94)." (PMID 36685922, 2022). "Indeed, another study reported a CCL5 pro-tumour activity in breast cancer pulmonary metastasis, associating CCL5 with macrophages recruitment in breast cancer distant colonisation." (PMID 35406451, 2022). "For example, CCL5 was associated with breast cancer grade and metastasis." (PMID 34503058, 2021). "In addition, overexpression of CCL-5 in HER2-positive breast cancer is associated with poor disease-free survival and lower overall survival." (PMID 34944905, 2021). "These previous findings are in agreement with our present study, and the CCL5/CCR5 axis may be associated with the less aggressive phenotype of breast cancer in contrast to CCR3." (PMID 33671956, 2021). "A number of studies have implicated CCL5 in the recruitment of macrophages to mammary tumors." (PMID 34298673, 2021).